LDHA (lactate dehydrogenase A)
Diseases named in the same sentence as LDHA in open-access papers (continued):
Sharing a sentence is not in itself a finding about the gene and the disease.
melanoma (102 papers, 2012 to 2025). A malignant, usually aggressive tumor composed of atypical, neoplastic melanocytes. "Intriguingly, investigations have shown that B16-F10 melanoma tumors deficient in LDHA exhibit increased infiltration of NK cells and CD8+ T cells." (PMID 39990209, 2025). "For example, in melanoma, LDHA‐associated lactic acid accumulation inhibits tumor surveillance by T and NK cells." (PMID 40244859, 2025). "In mouse models with LDHA-deficient melanoma tumors, there was a significant increase in the infiltration of natural killer cells and CD8+ cytotoxic T cells, leading to elevated IFN-γ expression." (PMID 40535811, 2025). "Here, we show that there exists a direct correlation between serum and tumor LDH in a mouse melanoma model and that, in melanoma patients, tumor LDHA is associated with shorter survival." (PMID 39225102, 2024). "Consistent with this, other researchers have found that mice with lactate dehydrogenase A (LDH-A) deficient B16-F10 melanoma have a better response to anti-PD-1 treatment, which is manifested by increased infiltration of NK cells and CD8 + cytotoxic T cells." (PMID 38779665, 2024). "Consistently, we found elevated LDHA expression in human melanoma samples from TCGA is associated with poorer survival." (PMID 39225102, 2024). "Excess LDHA expression and/or activity have been directly linked to a variety of clinical conditions including Non-Hodgkin Lymphoma, melanoma, gastric cancer, non-small cell cancer, and the aging brain." (PMID 29795645, 2018). "In addition, the administration of anti-PD-1 therapy has been shown to augment the anti-tumor immune response in melanoma-bearing mice generated from LDHA-deficient B16-F10 cells." (PMID 39990209, 2025). "For example, LDHA (lactate dehydrogenase A)-associated lactic acid accumulation in melanomas inhibits tumor surveillance by T and NK cells, and LDHA mediated lactate production suppresses IFN-γ expression in both tumor-infiltrating and immune evasion murine models." (PMID 35686268, 2022). "We compared the expression levels of LDHA in melanoma and normal tissues and found that LDHA was significantly overexpressed in melanoma." (PMID 39990209, 2025). "Here, we identified lactate dehydrogenase A (LDH‐A) as a crucial player in modulating sex‐related differences in melanoma immune responses, both in vitro and in patient‐derived specimens." (PMID 39888245, 2025). "To investigate the clinical relevance of glycolysis in melanoma, we focused on the key enzyme LDHA in aerobic glycolysis and examined a series of expression and survival datasets from melanoma patients." (PMID 39990209, 2025). "LDHA-IN3 and Azm-33 are LDHA inhibitors with unclear mechanisms, which have been shown to inhibit melanoma proliferation and promote cell death in breast and colon cancers, respectively." (PMID 39683818, 2024). "By elucidating the interaction between BAP1 and LDHA and the subsequent effects on lactate production in melanoma cells, this work provides insights into the mechanism of BAP1-mediated metabolic regulation." (PMID 39587076, 2024). "Upon reanalyzing single-cell RNA-Seq (scRNA-Seq) data from human melanoma samples, we confirmed that malignant cells within the tumor overexpress LDHA compared with CD8+ tumor-infiltrating lymphocytes (TILs)." (PMID 39225102, 2024). "Studies have shown that elevated expression of lactate dehydrogenase A (LDHA) in melanoma increases lactate synthesis and release, inhibiting the antitumor activity of NK cells and leading to tumor immune escape." (PMID 39769177, 2024). "Further literature review revealed that overexpression of NAC1 in tumors can promote the progression of melanoma through LDHA-mediated immune escape." (PMID 38704368, 2024). "We previously demonstrated that the expression of genes involved in glucose metabolism, including LDHA, negatively correlates with immune cell infiltration in a small cohort of patients with melanoma." (PMID 39225102, 2024).
melanoma (continued). "In B16 melanoma tumors, this effect was dependent on both tumor LDHA expression and the presence of the adaptive immune compartment." (PMID 39225102, 2024). "Treating patient-derived melanoma with a lactate dehydrogenase A (LDHA) inhibitor, GSK2837808A, showed T-cell antitumor cytotoxicity." (PMID 38732242, 2024). "For example, B16F10 melanoma cells were still able to secrete substantial amounts of lactate following the elimination of either LDHA or LDHB alone." (PMID 37868977, 2023). "CCHE1 promoted the glycolysis and proliferation of melanoma cells by enhancing FGFR1-mediated LDHA phosphorylation and activation." (PMID 37480145, 2023). "Enhanced LDHA is an independent poor prognostic factor of nasopharyngeal carcinoma, non-Hodgkin lymphoma, cervical cancer, and melanoma." (PMID 37298317, 2023). "The therapeutic potentials of targeting CCHE1 and co-inhibiting FGFR1/LDHA in melanoma deserve more investigation by the in vivo studies." (PMID 37480145, 2023). "Lactate dehydrogenase A (LDHA) catalyzes the conversion of pyruvate to lactate, which is the last step of glycolysis and related to cancer development including melanoma." (PMID 37480145, 2023). "Significantly reduced cell proliferation was observed with the co-inhibition of FGFR1 and LDHA in CCHE1-depleted melanoma cells." (PMID 37480145, 2023). "Collectively, these results demonstrated that CCHE1 interacted with LDHA and modulated its activity in melanoma cells." (PMID 37480145, 2023). "In the study, we found that CCHE1 acted as a scaffold to facilitate the binding between FGFR1 and LDHA, which enhanced LDHA activity and glycolysis of melanoma cells." (PMID 37480145, 2023). "Melanoma cells, however, stopped proliferating under hypoxic conditions following the simultaneous elimination of both LDHA and LDHB." (PMID 37868977, 2023). "For example, in melanoma patients, the LDHA and lactate levels in tumors are negatively correlated with antitumor CD8+ T-cell activity and overall patient survival." (PMID 36854755, 2023). "Significantly reduced melanoma cell proliferation and glycolysis were observed with co-inhibition of FGFR1 and LDHA in CCHE1-depleted cells, suggesting the key function of CCHE1/FGFR1/LDHA regulatory axis in melanoma." (PMID 37480145, 2023). "CCHE1 bound LDHA and modulated its activity in melanoma glycolysis via regulating FGFR1-mediated LDHA phosphorylation." (PMID 37480145, 2023). "Second, the expression of NAC1 contributes to immune evasion through its regulatory role in LDHA expression and lactic production in melanoma." (PMID 37626718, 2023). "Another study indicated that the use of the inhibitor GSK2837808A to suppress LDHA in both patient-derived and B16 melanoma cells can enhance the functionality of T cells both in vitro and in vivo." (PMID 38071310, 2023). "This seems to be largely dependent on the level of LDHA activity, as shown by studies comparing the growth of tumors from control melanoma or LDHA-shRNA knock-down (Ldhalow) cells." (PMID 35205318, 2022). "Studies found that the accumulation of LDHA-related lactic acid in melanoma can repress the function and activity of T cells and NK cells, leading to immune escape of tumors." (PMID 36213576, 2022). "Among malignant melanoma patients receiving PD-1 blockade therapy, patients with high LDHA expression show more significant ICB resistance and shorter progression-free survival (PFS)." (PMID 36620597, 2022). "These authors found that manipulating LDHA levels in a mouse model of melanoma results in more infiltrating NK cells and greater expression of IFNγ and granzyme B and greater tumor control in low-LDHA tumors compared to controls." (PMID 35414042, 2022). "To address the biological significance of K222 succinylation in vivo, we performed mouse melanoma lung metastasis experiments using B16-F10 cell lines overexpressing WT, K222R or K222E mutant LDHA." (PMID 32859246, 2020).
melanoma (continued). "For example, a novel circRNA circMYC promotes the proliferation and glycolysis of human melanoma cells by directly binding to miR-1236, as a miRNA sponge, then targets LDHA to accelerate the glycolysis." (PMID 32513983, 2020). "LDHB has been reported to complement the role of LDHA in colon adenocarcinoma and melanoma models with metabolic pressure." (PMID 33324565, 2020). "LDHA abrogation in the murine B16F10 melanoma model improved response to anti-PD-1 treatment, accompanied by an increase in tumor infiltration of CD8+ T cells and NK cells, increase in production of IFN-γ and granzyme B, and decrease in Treg infiltration." (PMID 33324565, 2020). "In our previous work, we clearly demonstrated in a murine B16 melanoma model, that inhibition of lactate production by LDHA downregulation improves immunosurveillance and restrains tumor in an IFN-γ dependent manner." (PMID 31334125, 2019). "The expression levels of GLUT1, GLUT3, HK2 and LDHA mRNA were downregulated in melanoma cells incubated with the HLA-B,C-specific mAb B1.23.2." (PMID 31454998, 2019). "Melanoma has been described to be highly glycolytic, due to upreguation of glucose transporters and lactate dehydrogenase-A (LDH-A)." (PMID 28595656, 2017). "With the melanoma B16 Gpi-KO cell line developed here or the LDHA/B-DKO (unpublished data) in which lactic acidosis is substituted for carbonic acidosis (OXPHOS-dependence), this important question should be simple to address experimentally." (PMID 29152106, 2017). "Further, to confirm the involvement of LDH in melanoma cell growth and proliferation, knock down of LDHA (LDHA-KD) was performed using specific siRNA." (PMID 26484566, 2015). "This conclusion is based on the finding that LDHA was elevated in primary melanomas compared with nevi, and was even more elevated in thick (Breslow thickness of invasion > 2 mm) primary melanomas." (PMID 23043612, 2012). "circMYC (hsa_circ_0085533) is markedly up-regulated in melanoma tissues and promotes tumor cell proliferation, driving glycolytic flux; sponging off the tumor suppressor miR-1236, circMYC relieves LDHA repression, leading to increased rates of extracellular acidification and lactate production." (PMID 40573249, 2025). "Furthermore, LDHA/LDHB deficiency also diminished glycolysis and STING activation in tumor-infiltrating DCs and impaired DC antitumor immunity in B16-F10 melanoma model." (PMID 36821379, 2023). "SOX4 regulates melanoma glycolytic metabolism controlling the transcriptional expression of glucose transporter type 1, hexokinase 2, and lactate dehydrogenase A, and activates mTORC1 to promote proliferative signals and cell growth when SOX4 is upregulated by CD147." (PMID 36661515, 2023). "Another study demonstrated that inhibition of patient-derived and B16 melanoma LDHA with the inhibitor GSK2837808A could enhance T cell function in vitro and in vivo and enhance adoptive cell therapy." (PMID 36233246, 2022). "Additionally, LDHA was negatively associated with the T‐cell activation markers (granzyme K and CD25) in human melanoma." (PMID 36518315, 2022). "Pathria and colleagues demonstrated that, in melanoma, adaptation to Lactate Dehydrogenase A LDHA inhibition, meant to disrupt the “Warburg effect,” is mainly associated with activation of the ISR, which in turn increases glutamine uptake and mTORC1 activation." (PMID 35912100, 2022). "Moreover, a recent study reported that the shRNA-mediated blockade of LDHA improved the efficacy of anti-PD-1 therapy by enhancing T-cell infiltration in melanoma." (PMID 36518315, 2022). "Interestingly, the number of cytotoxic effector cells was increased in melanoma-bearing mice in which lactate production was significantly lowered by the silencing of the lactate dehydrogenase A enzyme." (PMID 33499083, 2021).
melanoma (continued). "Moreover, combining the LDHA inhibitor GSK2837808A with ACT in a syngeneic murine melanoma model profoundly improved the anti-tumor response and survival compared to either LDHA inhibition or ACT alone." (PMID 33324565, 2020). "A significant increase of LDHA expression was present in all melanomas." (PMID 31781212, 2019). "Interestingly, they also demonstrated that blocking LDHA in tumor cells improves the efficacy of anti-programmed cell death-1 (PD-1) therapy in melanoma." (PMID 31737570, 2019). "As demonstrated in samples of melanoma patients showing that high LDHA expression is associated not only with poor prognosis, reduced disease-free survival, but also with lower expression of T cell markers." (PMID 31737570, 2019). "In melanoma, Arseneault et al72 found that LDHA inhibition resulted in mitochondrial ROS accumulation, which may alter the structure of tropomyosin via oxidation." (PMID 30403008, 2018). "Therefore, targeting glucose transporters and other enzymes (such as LDHA) that are involved in glycolytic metabolism in melanoma cells is a potentially attractive therapeutic option for the treatment of melanoma." (PMID 29209327, 2017). "Hence, authors proved that melanoma patients with high LDHA levels possess high extracellular lactate levels and are therefore associated with poor prognosis." (PMID 28798748, 2017). "In melanoma patients, LDHA expression correlated with T cell activity and LDHA-associated lactic acid production and acidification impaired IFNγ expression in tumor-infiltrating T cells and NK cells, thereby inhibiting tumor immunosurveillance and promoting tumor growth." (PMID 28337200, 2017). "To investigate whether melanoma cells express LDHA that mediates conversion of pyruvate to lactate, we performed immunohistochemistry studies of a nevus>melanoma progression TMA." (PMID 23043612, 2012). "Pairwise comparison between different stages of the nevus>melanoma progression pathway showed that the most significant increase was between primary thick primary melanomas and nevi, with the mean LDHA expression increased approximately three-fold (Wilcoxon adjusted p=0.003)." (PMID 23043612, 2012). "However, the regulatory mechanism of LDHA activity and the physiological significance of LDHA inhibition in melanoma remain largely unknown." (PMID 37480145, 2023). "Indeed, preclinical evidence suggests that blocking LDHA in the tumor might improve the efficacy of anti-PD-1 therapy for melanoma." (PMID 36077374, 2022). "However, LDHA was found to be highly expressed in most cancer cells, which is the main reason why LDHA can be used as a biomarker of many malignant tumors, such as gastric cancer, testicular germ cell tumor, glioma and melanoma." (PMID 36059961, 2022). "In vitro, administration of lactic acid inhibited proliferation and activation of human cytotoxic CD8 T cells, while LDHA-mediated production of lactate in tumor cells constrained IFN-γ production in tumor-infiltrating T cells, resulting in a loss of immune surveillance in a mouse melanoma model." (PMID 31334125, 2019). "LDHA inhibitors combined with PD‐1 blockade show synergistic antitumor effects in NSCLC and melanoma models." (PMID 40443721, 2025). "Lactylation enhances the expression of LDHA and MCT4 in melanoma cells, promoting lactate metabolism, tumor proliferation, and drug resistance." (PMID 41458606, 2025). "Our findings align with a previous study in which double knockout of LDHA and LDHB in human colon adenocarcinoma (LS174T) and murine melanoma (B16-F10) cells led to a two-fold reduction in growth rates compared to wild-type cells." (PMID 41279318, 2025). "On the functional level, the double-knockout of LDHA and LDHB rendered murine melanoma and human colorectal adenocarcinoma cells more sensitive to RT7." (PMID 40158058, 2025).
melanoma (continued). "Results demonstrated that the presence of free zinc ions led to a concentration-dependent inhibition of LDHA activity and an elevation in LDH efflux, invigorating PTT treatment and synergistically suppressed primary melanoma and lung metastasis." (PMID 39934144, 2025). "We also compared mRNA expression of glycolytic markers in p3-S melanoma cells respect to S melanoma cells and we confirmed that in anoikis-resistant cells the expression of GLUT1, GLUT3, HK2, PKM2, and LDHA significantly reduced." (PMID 39175551, 2024). "This study aimed to disrupt the energy metabolism within melanoma tumors by targeting LDH enzymes, specifically LDHA and LDHB, with the goal of enhancing the efficacy of ICI treatments." (PMID 39435293, 2024). "In this work, KIF22 interference notably repressed glycolysis in melanoma cells, evidenced by reduced levels of ECAR, lactate production, HK2, PKM2 and LDHA expression as well as elevated levels of OCR." (PMID 37944197, 2023). "Herein, we verified that the circ_0013359 level was conspicuously increased in melanoma and its reduction repressed melanoma cell glycolysis by reducing glucose consumption, lactate production, ECAR, HK2, and LDHA." (PMID 34056112, 2021). "Conversely, reducing LDHA-mediated lactic acid production has been found to enhance T cell-mediated tumor killing, improve IFN-γ-producing T cell infiltration, and reduce melanoma tumor size." (PMID 33324565, 2020). "The absence of increased LDH5 in patients with high serum LDH can be explained by the significant positive correlation between LDHA and LDHB expression in melanomas and that more LDHB than LDHA proteins are upregulated in advanced melanomas." (PMID 23043612, 2012). "Since it has been reported that HIF-1α increases LDHA expression, we also determined HIF-1α expression in the nevus>melanoma TMA." (PMID 23043612, 2012). "In addition, work using murine melanoma cells and LS174T colorectal adenocarcinoma cells demonstrated that Oxamate reduces radioresistance by inhibiting LDHA activity." (PMID 40565174, 2025). "This aligns with recent findings suggesting that both LDHA and LDHB contribute to pyruvate-to-lactate conversion, requiring the simultaneous knockout of both LDHA and LDHB to stop lactate production in LS174T (human colorectal adenocarcinoma) and B16-F10 (mouse melanoma) cell lines." (PMID 39435293, 2024). "Interestingly, data from a recent study suggest that LDHB expression is required for energy metabolism in hypoxia, as knockout of both LDHA and LDHB were required to restrict growth of human colon cancer and mouse melanoma cell lines." (PMID 37107600, 2023). "Several cytosolic (PGM2, LDHA and pPKM2) and mitochondrial (UQCRC1, COX4 and ATP5B) enzymes are downregulated by HPF treatment, suggesting a generalized reduction of vital functions in melanoma cells." (PMID 36674794, 2023). "Additionally, GNE-140, which targets both LDHA and LDHB, was sufficient to mimic the effect of the simultaneous elimination of both isoforms in melanoma cells in terms of inhibition of glycolysis and reactivation of oxidative phosphorylation in WT cells." (PMID 37868977, 2023). "Considering the important role of LDHA in aerobic glycolysis, the interaction of CCHE1 with LDHA might affect the glycolysis of melanoma cells." (PMID 37480145, 2023). "In a mouse melanoma model, an increase in IFN-γ and granzyme B production in NK cells and CD8+ T cells as well as an increase in PD-1 antitumor immune responses to immune checkpoint inhibitors have been reported by blocking LDHA can be observed." (PMID 38071310, 2023). "Additionally, the proliferation of melanoma cells that were co-treated with inhibitor of FGFR1 PD166866 and LDHA inhibitor GSK2837808A was detected by CCK-8 assay." (PMID 37480145, 2023).